IL6 (interleukin 6)
Diseases named in the same sentence as IL6 in open-access papers (continued):
Sharing a sentence is not in itself a finding about the gene and the disease.
infection (continued). "The results regarding the levels of cytokines studied in this work (IL-1β, IL-6, TNF-α) may suggest that the presence of intracellular C. trachomatis in the infection will play a dominant role in the immune system response." (PMID 40647668, 2025). "Consistent with the severe airway inflammation observed via histopathology analysis, sublethal infection with wild-type K7 boosted the secretion of the inflammatory cytokines TNF-α, IL-6 and IL-1β, whereas the levels of these cytokines were significantly reduced by IFA treatment." (PMID 39761301, 2025). "Furin inhibitors MI-1851 and MI-2415 decreased cytotoxicity and compensated for IL-6 and IL-8 overproduction in cells during infection with EHEC and S. flexneri, but not in cells exposed to EPEC." (PMID 40426498, 2025). "However, during the acute phase of infection, CX3CL1 receptor blockade increased TNF and IL-6 production in skeletal muscle." (PMID 40936920, 2025). "Recently, however, the activation of the Hedgehog and NOTCH signaling pathways following viruses’ infection (including SARS-CoV-2) has been reported to induce STAT3 upregulation, to increase IL-6 expression, and lead to the observed detrimental outcomes, such as fibrosis." (PMID 40156072, 2025). "While systemic inflammatory markers—including C-reactive protein (CRP), interleukin-6 (IL-6), and procalcitonin (PCT)—demonstrate sensitivity to infection, their specificity for IAI in SAP is limited, as they also reflect sterile inflammation and pancreatic necrosis." (PMID 40852356, 2025). "Concomitantly, genes involved in inflammatory and interferon-related responses, including IFN-γ, IL-12b, STAT1, STAT3, IL-6, TNF-α, CXCL9, CXCL10, and CXCL5, were significantly upregulated, indicating a strong pro-inflammatory environment during peak infection." (PMID 40630939, 2025). "This breed had medium levels of IL-6 without infection, with high levels being observed in Simmental and low levels in Holstein." (PMID 40302747, 2025). "When monitoring DFUs and VLUs, a set of key parameters, such as temperature, pH, hydration, and specific inflammatory biomarkers, like cytokines (i.e., IL-6 and TNF-α) and proteases (i.e., MMPs), can be used to assess wound status, detect early signs of infection, and guide treatment strategies." (PMID 39926013, 2025). "Interestingly, a similar increase was also seen after mock infection with heat-inactivated virus, but generally only at 3 and 6 hr (e.g., CXCL3 and IL6)." (PMID 39869630, 2025). "In the brain, infection with Bov342 induced the expression of type-I (Ifna5, Ifnb), -II (Ifng), and -III (Ifnl2) interferons (IFN), interferon stimulated genes (ISGs) (Isg15, Ifit1, Mx1, Oas1), and pro-inflammatory cytokines (Il1b, Il6, and Tnfa) at endpoint." (PMID 40410375, 2025). "Furthermore, ROC curve analysis demonstrated that serum TNF-α, IL-6, and IFN-γ levels have good predictive value for DFI infection severity and prognosis, and their combined detection further improves predictive accuracy." (PMID 40677522, 2025). "Notably, k-means clustering of the ES group PPI network identified three functional modules, with IL6 and FBL emerging as the most prominent hub nodes, suggesting their critical involvement in the host response to polymicrobial infection." (PMID 40771952, 2025). "However, in our study, in the high-dose infection group, elevated STAT1 and ISG expression were accompanied by a marked upregulation of pro-inflammatory cytokines, including IL-6 and TNF-α." (PMID 40941331, 2025). "Many up-regulated genes are closely related to inflammation and immune responses, such as CCL20, IL6, CXCL1, CSF1R, CCR5, TNFRSF8, indicating that mice infected N. farcinica via these two infection routes may lead to robust inflammatory response." (PMID 40723822, 2025).
infection (continued). "Compared with Mtb‐infected control macrophages, the level of IL1β was significantly reduced in both HIF1‐KD and GBP1‐KD cells after infection with HN878 or CDC1551, while TNFα and IL6 were significantly reduced only in HN878‐infected HIF1‐KD and GBP1‐KD macrophages." (PMID 41287823, 2025). "The levels of IL-6 and TNF-α in the supernatant and those of cellular proteins in Beas-2b cells infected with MP increased in a manner dependent on both the multiplicity of infection (MOI) and time." (PMID 41156647, 2025). "The levels of TNF-α, IL-6, IFN-γ, IP-10, MCP-1, and CCL3 were markedly elevated in the vehicle group, indicating that following infection with the influenza viruses, the lung tissues produced a plethora of proinflammatory mediators, thereby establishing an inflammatory milieu within the lungs." (PMID 40283905, 2025). "In our studies, wound tissue MCP-1, IL-6, and IL-10 levels were not significantly altered after 24 h of infection and LaP treatment tended to increase tissue IL-6 levels." (PMID 40068933, 2025). "Thus, cytokines such as IL-1β, IL-6, IL-8, and IFN-α play fundamental roles in orchestrating the immune system’s multifaceted response to injury, infection, and malignancy." (PMID 40284869, 2025). "Notably, IL-6 levels negatively correlated with CTLA4 and IDO1 expression, particularly in JBNU-22-N01 infection." (PMID 40459260, 2025). "The activation of NF-κB in macrophages initiates an inflammatory cascade and promotes their recruitment to sites of infection, where activated M1 macrophages secrete TNF-α, IL-1β, IL-6, and other cytokines to mobilize neutrophils and initiate the host response." (PMID 41347221, 2025). "Moreover, there were significant differences in TNF-α, IL-6, and IFN-γ levels among patients with mild, moderate, and severe infections (P<0.05)." (PMID 40677522, 2025). "We also detected inflammatory cytokines such as MCP-1, IL-6, IFN-β, and IL-1β in the serum of the CVB3-infected mice, with the results showing that these cytokines were highly expressed post-infection." (PMID 41356483, 2025). "In those who have experienced prior COVID-19 exposure, either via infection or immunisation, the immune system may remain primed as demonstrated by sustained elevations of inflammatory markers IL-6 and TNF-α for up to 12 months post-infection." (PMID 41303146, 2025). "Additionally, IL-6 can interact with GP130 on the cell membrane, inducing STAT3 phosphorylation and contributing to the onset and progression of infections." (PMID 41137299, 2025). "In the present study, we established a cohabitat infection model of ichthyophthiriasis in darkbarbel catfish, cloned the complete coding sequences (CDS) of IL-1β, IL-6, and SAA, and dynamically monitored their transcription levels by RT-qPCR throughout the infection period." (PMID 40509043, 2025). "Unlike other proinflammatory cytokines, IL-6 was detected in both uninfected and infected samples at 4 h post-infection, with a statistically significant increase observed only in rNRP1-infected explants (1.5-fold)." (PMID 41450943, 2025). "Constant activation of immune response through interleukin-6 (IL-6) and tumor necrosis factor-alpha (TNF-α) to recruit immune cells-such as leukocytes- to the site of infection can also impair vascular permeability and affect vascular pulsatility and astrocytic support function." (PMID 40502828, 2025). "Additionally, quantification of the levels of IL-1β, IL-6, and TNF-α pro-inflammatory cytokines showed that old murine BMMs displayed similar levels of IL-1β, IL-6, and TNF-α 24 h after infection with Aa or Pg compared with controls in young BMMs." (PMID 40649955, 2025). "Pooled evidence from 46 pediatric studies confirms that IL-6, Il-8, procalcitonin, and CRP remain the most validated biomarkers for early infection detection in pediatric febrile neutropenia, though their clinical utility depends on rigorous contextual interpretation." (PMID 40647525, 2025).
infection (continued). "Several studies have highlighted that M. stadtmanae can activate human dendritic cells, triggering the release of pro-inflammatory cytokines such as TNF-α and IL-6, suggesting potential immunopathogenic effects even in the absence of overt infection." (PMID 41305349, 2025). "Thus, we evaluated serum cytokine levels, such as IL-1β, IL-6, IL-10, MCP-1, and IFN-γ in EV-A71 infected PLG-KO and WT mice at 2, 4, and 6 days post-infection." (PMID 40377310, 2025). "The results showed that, during PRV (MOI = 0.4) infection, compared to the empty vector group, all METTL3 groups (METTL3, METTL3-S43A, METTL3-S50A, and METTL3-S525A) significantly enhanced the mRNA transcription levels of IL-1β, IL-8, IL-6 and TNF-α." (PMID 40802811, 2025). "However, at 24 h post-infection, the expression levels of TNF-α, IL-1β, and IL-6 were markedly reduced, while the secretion of the chemokine IL-8 continued to increase, and the anti-inflammatory cytokine IL-10 was significantly upregulated (P < 0.05)." (PMID 40874199, 2025). "Compared with non-anti-IL-6 bDMARDs, the rate of infections recorded as ICD-10 codes in secondary care data was significantly higher in anti-IL-6 bDMARD-treated patients before treatment [difference 8.8% (95% CI 1.1." (PMID 39698233, 2025). "Since, in contrast to CRP, IL-6 already peaks within 24 hours from the start of surgery, we hypothesized that IL-6 would be superior to CRP in predicting postoperative infection on the first postoperative morning after pulmonary surgery." (PMID 40549692, 2025). "Multiple studies have demonstrated that biomarkers such as IL-6, PCT, IL-10, and IL-8 offer superior sensitivity and specificity compared to conventional markers like CRP, particularly in the early phase of infection and in differentiating between bacterial and viral etiologies." (PMID 40647525, 2025). "Irrespective of the CovR/S variant used for infections, all three cell types released comparable levels of IFN-γ, tumor necrosis factor (TNF)-α, MCP-1, IL-6, IL-10, IL-12p70, and IL-23." (PMID 38408992, 2024). "The results indicated a significant increase in the mRNA and protein expression levels of the inflammatory cytokines IL-6, IL-10, and TNF-α 48 h after H37Rv-RFP infection compared with levels in the controls (hLO alone, M. tb-infected hLO, and hLO containing hMφs)." (PMID 39052544, 2024). "Without infection, the serum IL-6 level is very low, but it increases rapidly and sharply during the early stage of bacterial infection, while IL-10 is a potent anti-inflammatory cytokine that works to prevent inflammatory and autoimmune pathologies." (PMID 39195804, 2024). "In addition, quercetin can inhibit the exaggerated inflammatory response following infection via subsiding the expression of TNF-α, IL-1β, and IL-6 in macrophages." (PMID 39575436, 2024). "As expected, the presence of the sterile catheter segment alone resulted in ~8-fold induction of IL-6 in the absence of infection, but no further increase in IL-6 was observed during infection with V587." (PMID 38842305, 2024). "The protein levels of IFN-γ and IL-6 were significantly increased in the sera on day 3 after MA10 infection, whereas those of TNF-α were not." (PMID 38634132, 2024). "However, the engrafted hepatocytes have an intrinsic capacity to induce innate immune responses to stress and infection, as evidenced by their expression of several cytokines (TNF, IL6, and type I interferons) signaling pathways." (PMID 39209804, 2024). "During infection, toxicity, and irritation conditions, there are high concentrations of inflammatory factors in serum, such as IL-6, IL-8, TNF, C-reactive protein (CRP), soluble glycoprotein 130 (SGP130, involved in IL-6 signal transduction, sCD30, and MCP-1)." (PMID 38415245, 2024). "Furthermore, quercetin significantly decreased the expression levels of Il-6, Il-8, Il-18 and Tnf-α, compared to the GPS infection group (p < 0.05)." (PMID 38927100, 2024).
infection (continued). "During the second round of phage therapy, the patient’s infection markers (CRP, IL-6) initially increased and then decreased, which may be related to the immune system’s response to Pseudomonas aeruginosa." (PMID 39760039, 2024). "Cerebrospinal fluid cytokine levels were elevated in 6 patients without infection before they became seizure free, and we detected increased IL-1β and IL-6 levels in these patients." (PMID 39006838, 2024). "Additionally, IL-6 > 84.00 pg/mL and PCT > 1.39 ng/mL on POD 3 were found to be independent predictors when we analyzed the predictors of postoperative infection." (PMID 38504206, 2024). "Interestingly, higher IL-6 and TNF-α levels were observed in BCG-infected mice after 90 days of infection as compared to Ms_Vc and Ms_Rv1509." (PMID 38803374, 2024). "In contrast, IL-6 and CRP are well-established markers of systemic inflammation and acute-phase responses, serving as sentinel indicators of host defense mechanisms activated in response to infection." (PMID 39066228, 2024). "Our data show that infection of MDMs with H1N1 does not increase the secretion of inflammation-related cytokines/IFN (including IL-6) regardless of the phenotype, yet the mRNA of IL-6 was selectively increased in M2-MDMs." (PMID 38261967, 2024). "The DEGs involved in cytokine signaling were upregulated following infection with RHDV2 and included inflammatory cytokines such as IL1α, IL-6, and IL-8, and chemokines such as CCL2, CXCL9, and CXCL11, which were significantly upregulated compared with the non-infected rabbits." (PMID 38675838, 2024). "In the triple-depletion model presented here, we found that treatment with M-T807R1/Clodrosome prior to infection resulted in an augmented inflammatory signature, as indicated by increased plasma IL-1β, IFN-γ, IL-10, IL-6, and IL-18 levels in the WT-infected animals." (PMID 38668247, 2024). "Moreover, we probed for the expression of proinflammatory cytokines mRNA, including Tnf, Il1b, and Il6, and found that their levels were significantly higher in the lungs of PM2.5-exposed mice upon infection." (PMID 38355515, 2024). "In addition, 48 or 72 h after antibiotics therapy, both the IL‐6 and CRP percentage changes showed the predictive ability of anti‐infection efficacy." (PMID 38967137, 2024). "After infection of CIECs with 106 CFU/ml C. jejuni 11168, Lior6 or 0097, the expression patterns of the interleukin (IL)-1β and IL-6 mRNAs, which are proinflammatory cytokines known to be upregulated after C. jejuni infection of chickens, were investigated via qRT‒PCR." (PMID 38907359, 2024). "Nevertheless, we demonstrated that the presence of TLR4 is very relevant to this process as the infection of shTLR4 cells with the co-culture failed to induce any increment in IL-6 expression compared to the non-infected control." (PMID 38612423, 2024). "It has been observed that while M. gallisepticum infection alone upregulates pro-inflammatory factors such as TNF-α, IL-1β and IL-6, the presence of M. gallisepticum-derived EVs results in a dose-dependent suppression of these factors in HD11 cells at 24 h post-infection." (PMID 38474071, 2024). "On the third day after infection, SARS-CoV-2 infection induced a significant increase in inflammatory cytokines and a high dose of GUANKE significantly reduced the induction of MCP-1 and IL-6." (PMID 39431894, 2024). "Interestingly, infection of Calu-3 cells with WT triggered a significantly higher secretion of TNF-α and IL-6 than galU−." (PMID 38470050, 2024). "In the first phase, tissue damage or infection leads to the release of inflammatory mediators (e.g., histamine, prostaglandins, leukotrienes, tumor necrosis factor (TNF), interleukin-1 (IL-1), and interleukin-6 (IL-6))." (PMID 39334802, 2024). "Thirdly, as this study was a retrospective analysis, some infection indicators were not routinely checked, so important inflammatory indicators such as IL-6 and procalcitonin were missed." (PMID 38590392, 2024).
infection (continued). "In contrast, high basal levels (>100 pg/mL) of IL-6 are known to be involved in CTCL pathogenesis, but no changes in both IL-6 and GM-CSF levels were observed after co-culture infection with H-1PV." (PMID 39123440, 2024). "As with the IV infection, Tax1bp1 led to a considerable non-statistically significant increase in IL-6 production and a substantial increase in IFN-γ in the serum." (PMID 39763950, 2024). "The mRNA levels of IL-1β, IL-6, and CCL20, which are known to trigger an inflammatory response, peaked at 6 h following infection with M. gallisepticum in HD-11 cells and tracheal epithelial cells, then gradually decreased and reached the baseline 24 h post-infection." (PMID 38474071, 2024). "During PRRSV infection, activated alveolar macrophages and other inflammatory cells secrete proinflammatory cytokines such as TNF-α, IL-1α/β, IL-6, IL-8, and IL-12, as well as TGF-β, to recruit neutrophils and lymphocytes to the site of infection and facilitate pathogen clearance." (PMID 38806818, 2024). "IL-6 levels in bovine MEC increased at 6 and 24 h after experimental infection with S. aureus." (PMID 38612339, 2024). "Both these cytokines, IL-17 and IL-6, were demonstrated to play a role in the progression of primary infection with LVS, but not against LVS secondary challenge or primary challenge with virulent F. tularensis." (PMID 38533334, 2024). "Taken together, these results highlight the potential intrinsic differences between LDGs and PMNs in their ability to release soluble mediators (IL-6 and MPO, respectively) while PUUV PMNs remain affected by the infection at the time of sampling by specifically releasing calprotectin." (PMID 39011044, 2024). "After infection with Streptococcus pneumoniae (S. pneumoniae), ATF3 regulates GPB5 or forms a complex with JUN, thus promoting the production of inflammatory cytokines (TNF-α, IL-1β, IL-6, and IFN-γ)." (PMID 38255898, 2024). "The secreted IL-6 levels in both YZU0463- and YZU2855- infected cells were similar and significantly higher than those in cells infected with YZU0463ΔfliC, YZU2855ΔfliC, and YZU2855fliC→fljB at both 3 h and 6 h post-infection." (PMID 39695896, 2024). "Compared to the medium, UV-inactivated RV16, filtered RV16, and the non-virus 0.1% DMSO infection medium did not significantly induce IL-6, CXCL8, or CCL5 protein release." (PMID 39598462, 2024). "Still, further studies are needed to define specific cut-offs and to evaluate ascites IL-6 in non-SBP infections." (PMID 38962151, 2024). "Furthermore, large cohort studies have revealed elevated levels of IL-1β, IL-6, and TNF in the serum of clinical patients with an average period of 8 months after infection." (PMID 38299028, 2024). "There was no significant change in IL-6 expression in the aorta with X31 infection and ASA and NCX4016 treatment at 3 and 6 dpi." (PMID 38638436, 2024). "Antibody-dependent enhancement (ADE) of infection, which would be expected to engage the FcΥR and potentially activate Vav/Rac/Rho signaling, results in upregulation of STAT3 and IL-6 during ZIKV and DENV infection and additionally downregulates ISGs, as reviewed." (PMID 38054722, 2024). "Furthermore, infection and tissue injury release the pro-inflammatory cytokines, including TNF-alpha, IL-1 beta, and IL-6, which contribute to subsection increased systemic inflammatory responses." (PMID 39048980, 2024). "The IL-6 gene expression appeared relevant only after one week post-infection for all the strains, with the highest levels detected for M. bovis SB1564, followed by the mixed infection, the MAP infection and M. bovis SB0841 infection." (PMID 38399810, 2024). "Following a longer 24-h infection, S.Tm∆invG and S.Tm∆4 did elicit above-background levels of IL-6 secretion, but still vastly lower than the >15,000 pg/ml noted for S.Tmwt." (PMID 38291037, 2024).